ZFHX4 (zinc finger homeobox 4)
Description:
May play a role in neural and muscle differentiation (By similarity). May be involved in transcriptional regulation.
Synonyms: ZFH4; FLJ20980; ZHF4
Tractability: PROTAC: UniProt records ubiquitination sites on it.
Gene: Protein-coding gene on chromosome 8 (76,681,239 to 76,867,281, forward strand). Ensembl gene ENSG00000091656.
Subcellular location: Nucleus
Subcellular location (Human Protein Atlas): Nucleoli fibrillar center; Nucleoplasm
Gene Ontology:
Molecular function: DNA-binding transcription factor activity, RNA polymerase II-specific; RNA polymerase II cis-regulatory region sequence-specific DNA binding; DNA binding; nucleic acid binding; zinc ion binding
Biological process: regulation of transcription by RNA polymerase II; regulation of DNA-templated transcription
Cellular component: chromatin; nucleus
Genetic constraint (gnomAD): Loss-of-function variants: 51 observed, 263.54 expected, observed/expected ratio (o/e) 0.19, 90% interval 0.15 to 0.24. The upper end of that interval is the gene's LOEUF score, 0.24, which puts it in group 1 of 6, group 1 being the genes least tolerant of losing a copy. Missense variants: 4,255 observed, 4,508 expected, observed/expected ratio (o/e) 0.94, 90% interval 0.92 to 0.97. Synonymous variants: 1,745 observed, 1,713 expected, observed/expected ratio (o/e) 1.02, 90% interval 0.98 to 1.06.
Gene-disease validity (ClinGen):
ClinGen rates the evidence that ZFHX4 causes each of these diseases.
syndromic complex neurodevelopmental disorder (autosomal dominant): Strong. A disorder that involves more than one phenotype associated with the central nervous system, including but not limited to intellectual disability, autism, and seizures (epilepsy), and also a distinctive pattern of other features including dysmorphisms and/or congenital malformations.
Homologues: Orthologues: chimpanzee ZFHX4 (99% identical), macaque ZFHX4 (99% identical), rabbit ZFHX4 (96% identical), pig ZFHX4 (96% identical), dog ZFHX4 (95% identical), rat Zfhx4 (92% identical), mouse Zfhx4 (92% identical), guinea pig ZFHX4 (81% identical), tropical clawed frog zfhx4 (80% identical), zebrafish zfhx4 (71% identical). Paralogues in human: ZFHX3 (55% identical), ZFHX2 (26% identical), LMX1B (4% identical), LHX1 (3% identical), LHX6 (3% identical), LHX4 (3% identical), LHX5 (3% identical), LMX1A (3% identical), LHX8 (3% identical), LHX9 (3% identical), LHX3 (3% identical), LHX2 (3% identical), and 8 more.
Diseases named in the same sentence as ZFHX4 in open-access papers:
ZFHX4 is named in the same sentence as 62 diseases in open-access papers, as found by Europe PMC text mining. Sharing a sentence is not in itself a finding about the gene and the disease. The quoted sentences say what the papers report.
glioblastoma (12 papers, 2017 to 2025). The most malignant astrocytic tumor (WHO grade IV). "ZFHX4 is a transcription factor and has been shown to be associated with the maintenance of tumor-initiating cells in glioblastoma." (PMID 37491302, 2023). "Higher expression of this gene may have contributed to the progression of this tumor as ZFHX4 has been associated with poor survival and metastasis in ovarian cancer and is reported to play a role in the maintenance of tumor-initiating cells in glioblastoma." (PMID 36937401, 2023). "Genetic deletions over the ZFHX4 locus have been associated with syndromic Peters anomaly, ocular abnormalities, and intellectual disability, and the protein plays a role in maintaining the undifferentiated, self-renewing state of glioblastoma tumour-initiating cells." (PMID 34780483, 2021). "ZFHX4 is required for the regulation of glioblastoma tumor–initiating cells, and its inhibition leads to reduced tumorigenesis and increased glioma-free survival time." (PMID 34368227, 2021). "The transcription factor ZFHX4 has been reported as required for maintenance of tumour-initiating cells in glioblastoma." (PMID 32734521, 2020). "ZFHX4 has a known role in nerve and muscle differentiation and was previously identified as a regulatory factor linking the chromatin-remodeling NuRD complex to the glioblastoma tumor-initiating cell state." (PMID 41458623, 2025). "Besides FP-RMS, in glioblastoma, CHD4 co-localizes with the transcription factor ZFHX4 and co-regulates a subset of its target genes to maintain the tumor-initiating cell population." (PMID 32744500, 2020).
lung adenocarcinoma (10 papers, 2017 to 2024). A carcinoma that arises from the lung and is characterized by the presence of malignant glandular epithelial cells. "ZFHX4 is also found as a prognostic factor for ovarian serous cystadenocarcinoma, esophageal cancer, and lung adenocarcinoma." (PMID 35975176, 2022). "In this study, we constructed a mRNA-mRNA related ceRNET of lung adenocarcinoma (LUAD) and identified the highlighted TWIST1-centered ceRNET, which recruits SLC12A5 and ZFHX4 as its ceRNAs." (PMID 31645542, 2019). "Moreover, in lung adenocarcinoma, poor prognostic factors of TWIST1 and ZFHX4 are targeted by miR-514a-3p, and ZFHX4 exerts oncogenic functions by regulating TWIST1." (PMID 33766100, 2021).
colon cancer (6 papers, 2020 to 2024). "Additionally, we examined the co-occurrence of mutations in TSPs and colon cancer mutation-prone genes, and found that TSPs coexisted mutationally with MUC16, FAT4, OBSCN, and ZFHX4." (PMID 38827236, 2024).
ovarian carcinoma (6 papers, 2022 to 2025). A malignant neoplasm originating from the surface ovarian epithelium. "Previous analysis of public data showed that ZFHX4 gene mutation was an independent prognostic factor of poor outcome in ovarian cancer." (PMID 40281612, 2025). "ZFHX4 has been associated with metastasis in ovarian cancer, hypothesized to be secondary to its ability to degrade the extracellular matrix." (PMID 41301029, 2025). "ZFHX4 has been proposed as a biomarker for poor prognosis in ovarian cancer and esophageal squamous cell carcinoma." (PMID 37445641, 2023). "ZFHX4 was proved to be an independent adverse prognostic factor for ovarian cancer patients (HR = 1.44, 95%CI: 1.13–1.83, p = 0.003)." (PMID 35915456, 2022). "For clinical applications, ZFHX4 was expected to be a prognostic biomarker for ovarian cancer metastasis." (PMID 35915456, 2022). "We also checked the effect of ZFHX4 on ovarian cancer patient’s prognosis using Kaplan–Meier Plotter." (PMID 35915456, 2022). "In ovarian cancer, elevated expression of ZFHX4 was also demonstrated to be correlated with poor outcomes, which was mainly influenced by metastasis, in bioinformatics databases and real-world cohort samples." (PMID 35915456, 2022). "In the future studies, clinical samples from ovarian cancer patients would be collected to detect the expressions of ZFHX4." (PMID 35915456, 2022). "In multivariable analysis, ZFHX4 was still proved to be an independent adverse prognostic factor for ovarian cancer patients (HR = 1.44, 95%CI: 1.13–1.83, p = 0.003)." (PMID 35915456, 2022). "Our results were in accord with these studies, which indicated that ZFHX4 reduced the survival times of ovarian cancer patients through promoting metastasis." (PMID 35915456, 2022). "GO and KEGG analysis indicated that EMT and matrisome alteration were key features during ovarian cancer progression, which were in line with the predicted functions of ZFHX4." (PMID 35915456, 2022). "In summary, based on the bioinformatics analysis, we hypothesized that ZFHX4 might promote metastasis in ovarian cancer by regulating EMT and reprogramming matrisome." (PMID 35915456, 2022). "Moreover, we firstly identified ZFHX4 as the hub gene contributing to the ovarian cancer metastasis, and EMT regulation and ECM remodeling were considered as its potential mechanisms." (PMID 35915456, 2022). "As enrichment analysis also implied that ion channels might play an important role in ovarian cancer metastasis, we further analyzed the relationships between ZFHX4 and ion trans-membrane transporters using gene sets from GO datasets (GO: 0,015,318)." (PMID 35915456, 2022). "On the one hand, ZFHX4 could be used to predict occurrence of metastasis in ovarian cancer patients, especially for those have completed therapy and were undergoing follow-up; On the other hand, the expression of ZFHX4 is prognostic for survival outcomes of ovarian cancer patients with metastasis." (PMID 35915456, 2022). "To better understand the potential mechanisms of the hub gene in promoting metastasis in ovarian cancer, we explored the common pathways in which ZFHX4 might be involved in using ovarian cancer samples from TCGA database by R software GSVA package via ssGSEA algorithm." (PMID 35915456, 2022). "ZFHX4 might promote metastasis in ovarian cancer by regulating EMT and reprogramming ECM." (PMID 35915456, 2022). "However, the detailed mechanism by which ZFHX4 regulated metastasis of ovarian cancer remained unknown." (PMID 35915456, 2022). "Secondly, laboratory-based experiments have not been conducted to validate the mechanisms of ZFHX4 in metastasis in ovarian cancer." (PMID 35915456, 2022).
esophageal squamous cell carcinoma (4 papers, 2017 to 2024). Esophageal squamous cell carcinoma (ESCC) is a type of esophageal carcinoma (EC) that can affect any part of the esophagus, but is usually located in the upper or middle third. "Mutations in ZFHX4 were strongly associated with poor prognosis and the down-regulation of ZFHX4 inhibits the progression of esophageal squamous cell carcinoma." (PMID 28694483, 2017). "There are frequent mutations in ZFHX4 in esophageal squamous cell carcinoma." (PMID 37215130, 2023).
lung carcinoma (4 papers, 2021 to 2024). "Somatic mutations in the ZFHX4 gene are associated with poor overall survival in Chinese lung cancer patients." (PMID 34970479, 2021). "It has been reported that TTN/ZFHX4 missense triggered the development of tumor-associated antigens and could predict a good prognosis in lung cancer." (PMID 35178154, 2022). "Finally, EIF4G1 displays diverse interactions in LUSC, linking with LUAD-related ZFHX4, COL6A6, and unusual PLPPR3 connections to lung cancer genes." (PMID 38389572, 2024).
ptosis (3 papers, 2019 to 2021). The drooping of the upper eyelid. "Its downstream TG was ZFHX4, which was a known causal gene for “Congenital Ptosis”55." (PMID 33824393, 2021). "Analysis revealed one missense alteration G12411T of Zinc Finger Homeobox 4 (ZFHX4) gene in one participant among 10 with congenital ptosis and another missense variation T > C P. Y374 C of Signaling Receptor and Transporter Retinol 6 (STRA6) gene in one participant among 3 with microphthalmos." (PMID 32962661, 2020). "One missense alteration G12411T of ZFHX4 gene was identified in patient with congenital ptosis." (PMID 32962661, 2020). "ZFHX4 has an unknown function, but it has been suggested as a candidate gene for ptosis and to be involved in neural and muscle differentiation based on the expression pattern." (PMID 30927068, 2019).
basal cell carcinoma (2 papers, 2021 to 2022). A carcinoma involving the basal cells. "ZFHX4 is one of the nine under-expressed genes and is a susceptibility locus of cutaneous basal cell carcinoma." (PMID 35681785, 2022). "ZFHX4 is one of the 9 under-expressed genes and is a susceptibility locus of cutaneous basal cell carcinoma." (PMID 33498739, 2021).
colorectal cancer (2 papers, 2024). A primary or metastatic malignant neoplasm that affects the colon or rectum. "In colorectal cancer cells, the expression of Zfhx4 has been computationally associated with the expression of transcripts that promote fatty acid oxidation." (PMID 39609254, 2024). "Some top-ranked candidates were PIM1 in bladder cancer (FDR ≈ 1%), ZFHX4 in colorectal cancer (FDR ≈ 1%), ERBB2 in prostate, stomach, breast luminal subtype, and bladder cancers (FDR ranging from 4% to 14%) and others." (PMID 39033140, 2024).
developmental delay (2 papers, 2021 to 2025). "This case shows potential overlap of clinical presentation due to multiple deleterious variants, of which the LMX1A variant is the strongest etiology of inner ear abnormalities in this patient while the ZFHX4 or ARHGAP4 variants may explain ID3’s developmental delay." (PMID 33924653, 2021).
orofacial cleft (2 papers, 2025). A disorder of facial skeleton that is characterized by cleft lip and/or cleft palate that result in feeding, speech and hearing problems caused by failures during development. "PubMed and DECIPHER database searches revealed nine individuals with syndromic/nonsyndromic forms of orofacial clefts carrying ZFHX4 variants or deletions affecting ZFHX4." (PMID 39702590, 2025). "Although ZFHX4 is a novel pathogenic gene associated with orofacial clefts in humans, its role in craniofacial development is largely unknown." (PMID 39320016, 2025). "Zfhx4 has been identified in mice and humans, and its mutations lead to orofacial clefts." (PMID 39320016, 2025).
age (1 paper, 2026). A temporal measurement of the time period elapsed since an identifiable point in the life cycle of an organism. "For example, ZFHX4 (cg02298862) and RBM38 (cg18523477) are involved in DNA damage response, signal transduction, and DNA binding processes central to aging and age‐related diseases such as cancer." (PMID 41482678, 2026).
angiosarcoma (1 paper, 2025). A malignant tumor arising from the endothelial cells of the blood vessels. "It is possible that ZFHX4 has a similar mechanism in angiosarcoma metastasis." (PMID 41301029, 2025).
cleft palate (1 paper, 2025). Cleft palate is a fissure type embryopathy that affects the soft and hard palate to varying degrees. "A study of nsCL/P and nonsyndromic cleft palate only (nsCPO) identified a significant enrichment of loss-of-function de novo variants in two genes, one of which was Zinc Finger Homeobox 4 (ZFHX4)." (PMID 39702590, 2025).
Congenital ptosis (1 paper, 2020). Congenital ptosis is characterized by superior eyelid drop present at birth. "We selected one alteration in the ZFHX4 gene, G12411T L4137F in the children with congenital ptosis." (PMID 32962661, 2020).
diabetic retinopathy (1 paper, 2023). "The association with pulse pressure and blood pressure have been associated to diabetic retinopathy through arterial stiffness and vision impairment, which has been identified in multiple genes, including the ZFHX4 gene, the SHANK3 gene, and the WNT9B gene." (PMID 37033211, 2023). "When investigating sub-phenotypes of T2DM, diabetic retinopathy has been identified to be associated with ACVRIC (rs4664229), ZFHX4 (rs61729527), WNT9B (rs4968281), SHANK3 (rs9616915), ZSCAN5A (rs7252603), and DCP1B (rs715146, rs1044950, rs113147414) gene." (PMID 37033211, 2023).
embryonal carcinoma (1 paper, 2017). A non-seminomatous malignant germ cell tumor characterized by the presence of large germ cells with abundant cytoplasm resembling epithelial cells, geographic necrosis, high mitotic activity, and pseudoglandular and pseudopapillary structures formation. "One study reported that ZFHX4 expression is required in differentiating P19 embryonal carcinoma cells and C2C12 myoblasts, highlighting the important roles of ZFHX4 in neural and muscle development." (PMID 28694483, 2017).
endometrial cancer (1 paper, 2025). Primary or metastatic malignant neoplasm involving the endometrium (mucous membrane that lines the endometrial cavity). "ZFHX4, a transcription factor implicated in chromatin dynamics, has been associated with increased genomic instability in other tumor types and may similarly contribute to aggressive tumor behavior in endometrial cancer." (PMID 40281612, 2025).
ependymoma (1 paper, 2012). A WHO grade II, slow growing tumor of children and young adults, usually located intraventricularly.
esophageal adenocarcinoma (1 paper, 2017). A malignant tumor with glandular differentiation arising predominantly from Barrett mucosa in the lower third of the esophagus. "As ZFHX4 mutations significantly contributed to poor survival of Chinese ESCC patients, we further examined the prognostic role of ZFHX4 mutations in 12 cancer types investigated by TCGA including ESCC and esophageal adenocarcinoma (EAD) of Vietnam, Brazil, United States and other populations." (PMID 28694483, 2017).
hemorrhage (1 paper, 2026). Loss of blood from the vascular compartment to the exterior or into nonvascular body space as a result of rupture or severance of the blood vessels. "Zfhx4 administration confers partial protection against betaPix depletion-induced hemorrhage, establishing the novel association between the two." (PMID 41543887, 2026).
leukemia (1 paper, 2020). A malignant (clonal) hematologic disorder, involving hematopoietic stem cells and characterized by the presence of primitive or atypical myeloid or lymphoid cells in the bone marrow and the blood. "These include mutations in genes known to cooperate with CBF-rearrangements [e.g. NRAS (n = 6), KRAS (n = 4), FLT3 (n = 2), KIT (n = 3), ZBTB7A (n = 2)] as well as in genes, which have not been described to be mutated in CBF leukemia so far (e.g. ZFHX4, NFE2, HERC1)." (PMID 31896782, 2020).
liver cancer (1 paper, 2023). An epithelial or non-epithelial malignant neoplasm that arises from the liver. "The authors examined the expression of ZFHX4 in TCGA database and discovered that the aberrant expression of ZFHX4 was also correlated to the poor prognosis of liver cancer patients." (PMID 35780460, 2023).
lymph node metastasis (1 paper, 2019). "High expression of the TWIST1-ceRNET components was significantly correlated with lymph node metastasis and advanced TNM staging (Lymph node metastasis: P = 0.025 for TWIST1, P = 0.005 for SLC12A5, P < 0.001 for ZFHX4; TNM stage: P = 0.008 for TWIST1, P = 0.015 for SLC12A5, P = 0.012 for ZFHX4;)." (PMID 31645542, 2019).
metastatic tumors (1 paper, 2025). "Compared with primary tumors, metastatic tumors more often displayed ZFHX4, FGFR1, MSI2, HIST1H1C, and TOP1 mutations, while MAPK7 mutations occurred only in primary tumors." (PMID 41301029, 2025). "Mutations in ZFHX4 (p = 0.0392), FGFR1 (p = 0.0436), MSI2 (p = 0.0437), HIST1H1C (p = 0.0467), and TOP1 (p = 0.0497) were significantly more common in metastatic tumors compared to primary tumors." (PMID 41301029, 2025).
microcephaly (1 paper, 2025). A congenital or acquired developmental disorder in which the circumference of the head is smaller than normal for the person's age and sex. "In addition, a homozygous ZFHX4 missense variant was identified by a clinical exome analysis of an individual with CL/P, microcephaly, and micrognathia born to unaffected parents carrying the variant in the heterozygous state." (PMID 39702590, 2025).
microdeletion syndrome (1 paper, 2021). "Thus, Zfhx4-deficient mice might be a suitable animal model to investigate the molecular mechanisms of palatal development and the pathogenesis of 8q21.11 microdeletion syndrome." (PMID 34732852, 2021).